INS (insulin)
Diseases named in the same sentence as INS in open-access papers (continued):
Sharing a sentence is not in itself a finding about the gene and the disease.
type 2 diabetes (continued). "Several cohort studies with long-term follow-up state that BCAA levels could be predictive of insulin sensitivity deterioration and type 2 diabetes development." (PMID 38539836, 2024). "Consequently, we expect to find improvement in insulin sensitivity after 3 weeks and a reduction in HbA1c after 12 weeks in people with prediabetes and type 2 diabetes." (PMID 38997765, 2024). "This higher insulin response to high protein intake could promote greater glucose control in healthy individuals as well as those with type 2 diabetes." (PMID 39796517, 2024). "Finally, the effects of switching from different basal insulin analogues to either icodec or glargine U100 were investigated in an open-label RCT including 154 participants with type 2 diabetes and a baseline HbA1c of 53–86 mmol/mol (7.0–10.0%)." (PMID 38679644, 2024). "In addition, it enhances insulin sensitivity, lowers fasting glucose levels, and reduces HbA1c concentrations in patients diagnosed with type 2 diabetes mellitus (T2DM)." (PMID 39130977, 2024). "Excess nutrient ingestion may stimulate insulin secretion, fat storage, and consequent type 2 diabetes." (PMID 39328982, 2024). "However, others have found that insulin alone can be a potent initiator of sympathetic responses prior to the development of type 2 diabetes." (PMID 38337589, 2024). "Interestingly, all participants with type 2 diabetes carrying a P/LP GLIS3 variant were treated with sulfonylureas, a class of medication that stimulates the secretion of insulin by activating ATP-dependent potassium channels." (PMID 38051360, 2024). "Whether magnesium supplementation improves insulin sensitivity in people with type 2 diabetes and a low serum magnesium level is unknown." (PMID 37922013, 2024). "Exercise improves glycaemic control, even in the absence of weight loss, and results in reduced body fat content and an increased insulin response Both aerobic and resistance exercises effectively improved insulin sensitivity and led to better glycaemic control in patients with type 2 diabetes." (PMID 38771888, 2024). "The PRISMA Study, carried out in Italy, demonstrated the reduction of HbA1c by structured SMBG combined with a dashboard illustrating mean pre- and post-meal blood glucose and magnitude of postprandial glucose excursion over 4 consecutive weeks in non-insulin-treated patients with type 2 diabetes." (PMID 37996773, 2024). "A larger (n=150) observational study of participants with type 2 diabetes on general hospital wards on multiple daily insulin injections showed that use of the GlucoTab CDS system was associated with a mean glucose level of 8.8 ± 1.8 mmol/l, with time in range (3.9–10.0 mmol/l) of 68.8%." (PMID 38953925, 2024). "Additionally, Mg enhances insulin sensitivity, making it vital in managing type 2 diabetes and improving metabolic health." (PMID 39539878, 2024). "These tissue-level ICWs also suggest that AKH is secreted in a strong pulsatile manner in larvae, a phenomenon similar to the pulsatile release of mammalian glucagon and insulin, which are disrupted in patients with type-2 diabetes, potentially contributing to hyperglucagonemia." (PMID 38947048, 2024). "Regularly consuming functional foods may improve antioxidant, anti-inflammatory, insulin sensitivity, and anti-cholesterol activities, which are important for preventing and managing type 2 diabetes." (PMID 38541047, 2024). "In particular, a randomized controlled trial (RCT) conducted on patients with type 2 diabetes mellitus (T2DM) showed that TN-based treatments led to a significant reduction in fasting plasma insulin and overall glycemic levels, with a notable correlation between ABA plasma levels and glycemia." (PMID 39796338, 2024). "Insulin may be used in adult MCS patients with pancreatitis due to poorly controlled Type 2 diabetes or in patients with Type 1 diabetes with diabetic ketoacidosis in whom hypertriglyceridemia is not uncommon." (PMID 38974610, 2024).
type 2 diabetes (continued). "An innovative approach to enhancing the metabolism of glycolipids and reducing the need for insulin secretion in obese and type 2 diabetes patients may involve stimulating brown adipose tissue and causing the browning of white adipose tissue." (PMID 39065709, 2024). "Similarly, vanadyl sulfate improves hepatic and muscle insulin sensitivity in patients with type 2 diabetes." (PMID 38675446, 2024). "Furthermore, “Glucagon signalling pathway”, “Type II diabetes mellitus” and “Insulin secretion”, all identified here as shared citrullinome pathways, have been identified to be linked target pathways for treatment in neuroinflammation, including in PD." (PMID 39456949, 2024). "The complex relationship between obesity and type 2 diabetes is largely mediated by IR, a condition influenced by factors like increased fatty acid flux, pro-inflammatory cytokines from adipose tissue, and impaired insulin signaling pathways." (PMID 38770513, 2024). "Our previous studies have confirmed that MSC-sEV can significantly reduce blood glucose levels in type 2 diabetic rats, promote insulin secretion, accelerate liver glycogen synthesis, and inhibit renal interstitial fibrosis in a unilateral ureteral obstruction rat model." (PMID 38890734, 2024). "The significant reduction in LysoPC levels in newly diagnosed type 2 diabetes (T2D) patients suggests disruptions in lipid signaling that may impair insulin sensitivity and glucose uptake." (PMID 39590846, 2024). "A recent study further demonstrated that the suppression of hepatic glucose production, measured via the clamp technique using tracer glucose, was accompanied by a reduction in glucagon levels and increased insulin secretion in subjects with type 2 diabetes administered 100 mg of vildagliptin." (PMID 40066124, 2024). "For instance, carrageenan, a thickening and stabilizing agent often used as additive in many UPFs, might contribute to the development of type 2 diabetes by impairing glucose tolerance, increasing insulin resistance, and inhibiting insulin signaling." (PMID 39328982, 2024). "Our previously published study demonstrated the association between constitutionally elevated blood serotonin and the symptoms of type 2 diabetes, namely, increased plasma levels of glucose and insulin, as well as higher glucose concentrations measured in metabolic assays." (PMID 39063084, 2024). "A growing body of research indicates that the composition of the gut microbiota may have a role in the onset of type 2 diabetes by influencing insulin sensitivity, intestinal permeability, energy balance, inflammatory regulation, and glycolipid metabolism." (PMID 39194579, 2024). "IPA analysis revealed that the enriched genes of acinar cells contributed to pathways relevant to digestive enzyme secretion or metabolism, such as pancreatic secretion, protein digestion and absorption, fat digestion and absorption, insulin secretion, type 2 diabetes, etc.." (PMID 38149757, 2024). "In one trial, which included 60 patients with type 2 diabetes who were non-insulin-dependent, a mixture of powdered Momordica charantia fruit, fenugreek seeds, and jamun seeds, uncooked or cooked, was consumed at a dose of 1g/day for 1.5 month and then 2 g/day for 1.5 month." (PMID 39796448, 2024). "Glucotoxicity may exert its deleterious effects on pancreatic β-cell function via a myriad of mechanisms, leading to impaired insulin secretion and, eventually, type 2 diabetes." (PMID 39056663, 2024). "Thus, we performed this randomized, case‐crossover study to compare Equil patch versus Traditional MMT‐712 insulin pump in type 2 diabetes using continuous glucose monitoring (CGM) metrics and profiles." (PMID 38599884, 2024). "Insulin resistance (IR), a condition in which peripheral tissues lose their ability to absorb glucose from the bloodstream in response to insulin stimulation, plays a crucial role in the development and progression of metabolic diseases such as type 2 diabetes." (PMID 38339185, 2024).
type 2 diabetes (continued). "However, our findings contrast with those of other clinical studies, in which acute administration of metformin was reported to have little effect on the insulin response to a standardised test meal in individuals with type 2 diabetes." (PMID 38561463, 2024). "Individuals with type 2 diabetes often experience impaired insulin secretion in the first phase, the study by T. Vilsbøll confirmed that liraglutide increased insulin secretion in both the first phase (approximately 2 min after the rise in blood glucose levels) and the second phase." (PMID 39598383, 2024). "Those with type-2 diabetes on insulin 16.8% had a hypoglycemic episode." (PMID 38827884, 2024). "Exogenous insulin may also be needed for Type 2 diabetics whose etiology stems from an acquired resistance to insulin." (PMID 39268600, 2024). "SENP1 plays a crucial role in insulin secretion in type 2 diabetes." (PMID 39431155, 2024). "Increased alanine consumption may be beneficial for metabolic disorders such as type 2 diabetes, as its addition to a cultured pancreatic beta cell line increases both glucose metabolism and the secretion of insulin." (PMID 39590829, 2024). "The upregulation of PPARγ and adiponectin, key regulators of glucose and lipid metabolism, suggests that M. oleifera extracts may improve insulin sensitivity and help restore normal glucose levels in patients with type 2 diabetes." (PMID 39458951, 2024). "Whether an increase in APOL genes can (negatively) influence insulin secretion and contribute to the inflammation-induced beta cell dysfunction that occurs in type 2 diabetes remains to be further investigated." (PMID 37924378, 2024). "The involvement of PNX-14 in regulating insulin expression and secretion from pancreatic β cells suggests a critical regulatory function in managing glucose homeostasis and treating conditions like type 2 diabetes." (PMID 39398330, 2024). "However, to date, no studies have investigated the impact of CGM in people with type 2 diabetes treated with mixed insulin; further research is required to evaluate the potential benefits in this group." (PMID 38951212, 2024). "Along with TRIM28 and NOTCH3, one of our most interesting discoveries in the ART placentas concerned the prominent downregulation of imprinted DLK1 as well as the pathways of insulin secretion and maturity onset diabetes of the young, which came forth in the DNAm analyses." (PMID 39702541, 2024). "However, in type 2 diabetes, cells exhibit reduced responsiveness to insulin, impeding glucose absorption and resulting in elevated blood sugar levels, termed hyperglycemia." (PMID 39634981, 2024). "The results suggested that when patients with type 2 diabetes first initiate insulin therapy, once-weekly insulin icodec may be the preferred treatment option." (PMID 39629047, 2024). "When assessed separately, patients with insulin-naïve type 2 diabetes (MD 0.45 kg; 95% CI 0.13 to 0.77 kg; I2 = 0%, p = 0.006) or treated with icodec (MD 0.54 kg; 95% CI 0.26 to 0.81 kg; I2 = 4%, p = 0.0001) had a significant weight gain compared to once-daily insulin." (PMID 39629047, 2024). "In a 12-week, double-blind, placebo-controlled study involving 64 individuals with type 2 diabetes (T2D), Sugar Shiftdemonstrated significant efficacy in stabilizing fasting glucose, lowering serum LPS levels, and improving insulin sensitivity as measured by the HOMA-IR index." (PMID 39770729, 2024). "Indeed, metabolic adaptive alterations can affect glucose–insulin metabolism, leading to obesity, IR, and type 2 diabetes (T2D) later in life." (PMID 39599588, 2024). "For example, people with type 2 diabetes with higher glucose levels are more likely to have vascular complications and require insulin therapy, and vascular complications (such as neuropathy and retinopathy) may be associated with falls." (PMID 38761257, 2024).
type 2 diabetes (continued). "Furthermore, previous studies have not characterized the metabolic repercussions across the full spectrum of patients with type 2 diabetes as studies often excluded individuals receiving insulin therapy." (PMID 38589596, 2024). "People with type 2 diabetes may have normal insulin concentrations or high insulin levels, but it is expected that their higher levels of blood sugar will result in even higher levels of insulin if their islets of Langerhans cells are functioning normally." (PMID 38314003, 2024). "Among people with type 2 diabetes, only one used isCGM and an insulin pump." (PMID 38376580, 2024). "Furthermore, most participants with type 2 diabetes were also prescribed insulin and encouraged to engage in health-promoting behaviors to control their HbA1c, while the mHealth interventions in this trial only targeted oral medication taking." (PMID 39211575, 2024). "One study suggests that natural killer (NK) cells may regulate insulin sensitivity and inflammation in type 2 diabetes." (PMID 38455849, 2024). "In this study, we explore the impact of SGLT2i and GLP1-ra therapy on the risk for developing diabetic retinopathy and DMO, through a real-world study from a global federated database, including around two million people with type 2 diabetes receiving insulin treatment." (PMID 38584180, 2024). "Therefore, the aim of this analysis was to assess if glucose and insulin responses to an MMTT can predict the development of type 2 diabetes." (PMID 38987291, 2024). "Swimming has been proven to enhance insulin sensitivity in type 2 diabetics, which may aid in the reduction of oxidative stress." (PMID 38645750, 2024). "Some studies have shown that the increase in the number of type 2 diabetes patients worldwide is related to factors such as overweight and obesity, and its mechanism may be its own insulin resistance." (PMID 39257903, 2024). "The first published trial was a 26 week double-blind, double-dummy RCT including 247 insulin-naive participants with type 2 diabetes inadequately controlled [HbA1c 53–80 mmol/mol (7.0–9.5%)] on metformin with or without a dipeptidyl peptidase-4 inhibitor (DPP4i)." (PMID 38679644, 2024). "In a sub-category of type 2 diabetes, a significant number of patients exhibit varying blood glucose levels due to obesity, independent of insulin, while others suffer from insulin deficiency or resistance." (PMID 39065795, 2024). "The insulin pathway is inhibited in type 1 and type 2 diabetes." (PMID 38243324, 2024). "In addition, several disease conditions, such as obesity and type 2 diabetes, result in chronic hyperinsulinemia due to an increase in insulin secretion and a decrease in insulin clearance." (PMID 38521788, 2024). "Remarkably, improvements in basal insulin sensitivity through chronic aerobic exercise in patients with type 2 diabetes were also accompanied by a re-arrangement of their intramyocellular lipid turnover which re-aligned their phenotype with that of the deconditioned athletes." (PMID 38750012, 2024). "We used a Mendelian randomization study to infer the role of each glycemic trait (fasting glucose, 2-h glucose, HbA1c, and fasting insulin) and liability to type 2 diabetes in metabolomic signatures with various sensitivity analyses and a reverse Mendelian randomization analysis." (PMID 38459184, 2024). "The mediation effect of type 2 diabetes and fasting insulin was less pronounced than that of BMI." (PMID 38583262, 2024). "Simplification of complex insulin regimen may be a durable option in at least one-half of patients with type 2 diabetes." (PMID 37787888, 2024). "Type 2 diabetes (T2D) is a metabolic condition of impaired insulin uptake and sometimes production." (PMID 39258167, 2024).
type 2 diabetes (continued). "This randomized, crossover clinical trial showed that compared to isocaloric IOM, a high-protein, low-fat DSNS containing low-glycemic carbohydrates reduced postprandial glycemic response while increasing GLP-1 and insulin response in people with type 2 diabetes." (PMID 38903056, 2024). "Moreover, the stress from job instability can elevate cortisol levels, reducing insulin sensitivity and increasing the likelihood of developing type 2 diabetes." (PMID 39867544, 2024). "Since, impaired insulin metabolism in the AD brain, therefore, intranasal insulin delivery in combination with empagliflozin (FDA-approved Type 2 Diabetes drug), is being evaluated clinically (NCT05081219) for mitigating AD and to enhances cognitive and memory abilities." (PMID 39122453, 2024). "Inducing type II diabetes in rats via NA/STZ injection is a well-established animal model, whereas STZ injection causes pancreatic B-cell damage, although NA partially protects insulin-secreting cells against STZ." (PMID 39055492, 2024). "Therefore, we also performed a statistical analysis of glycogen synthesis assay data in the subgroup of five men with type 2 diabetes with more in vitro insulin-resistant myotubes." (PMID 38814443, 2024). "There are several pathologies characterized by a decrease in the cell mass of insulin-producing β-cells up to an absolute deficiency, namely T1DM (type I diabetes mellitus), certain forms of MODY (maturity-onset diabetes of the young), or surgical interventions." (PMID 39045459, 2024). "This study explored the potential of saponins from Korean Red Ginseng to target the PINK1/Parkin mitophagy pathway, aiming to enhance insulin sensitivity in hepatocytes—a key factor in metabolic disorders like metabolic dysfunction-associated steatotic liver disease (MASLD) and type 2 diabetes." (PMID 38998642, 2024). "Therefore, our trial does not support routine use of magnesium supplementation in people with insulin-treated type 2 diabetes." (PMID 37922013, 2024). "The benefits of lifestyle interventions are mediated by mechanisms that improve glycemic variables and outcomes in type 4 and type 2 diabetes by increasing insulin sensitivity and reducing oxidative stress, which has been demonstrated in studies in other populations." (PMID 38231555, 2024). "In a rat model study, gefitinib improved insulin sensitivity in rats with type 2 diabetes." (PMID 38362147, 2024). "Increased FA binding to HSA, due to elevated FA levels, may contribute to altered insulin signaling dynamics in type 2 diabetes by reducing the capacity of HSA to compete with insulin for Zn2+ binding." (PMID 38750995, 2024). "PGZ is a drug used to improve insulin sensitivity in patients with type 2 diabetes." (PMID 38511769, 2024). "An experimental study in mice demonstrated that beta-cell-specific expression of Nox5 might be an important factor aggravating the high-fat diet-induced impairment of islet insulin secretion and β-cell failure in type 2 diabetes." (PMID 39529984, 2024). "Obesity impairs tissue insulin sensitivity and signaling, promoting type-2 diabetes." (PMID 39033139, 2024). "Besides, MNAM also improves hepatic insulin sensitivity of mice with type 2 diabetes via activation of SIRT1 and inhibition of forkhead box O1 (FOXO1) acetylation." (PMID 38029302, 2024). "Physical activity is a cornerstone in the prevention and treatment of type 2 diabetes, largely because physical activity may enhance insulin sensitivity substantially." (PMID 38921470, 2024). "The GRADE trial assessed four mediations currently in use with metformin for the maintenance of type 2 diabetes, including insulin glargine, a long-acting insulin analog; liraglutide, a GLP-1 agonist; glimepiride, a sulfonylurea; and sitagliptin, a DPP-4 antagonist." (PMID 39149678, 2024).